FTO (FTO alpha-ketoglutarate dependent dioxygenase)
Diseases named in the same sentence as FTO in open-access papers (continued):
Sharing a sentence is not in itself a finding about the gene and the disease.
Obesity (continued). "Suppressing the FTO protein is one of many mechanisms that could mitigate the development of metabolic syndrome, including obesity.The overexpression of FTO may enhance fat storage and contribute to obesity, as this protein is crucial for regulating fat accumulation." (PMID 39494311, 2024). "However, in multivariate logistic regression models, neither the FTO-rs9939609 nor the personality traits were associated with obesity." (PMID 39130748, 2024). "This review aims to consolidate current understanding regarding the implications of FTO in health and disease, with a special emphasis on its involvement in obesity and non-communicable diseases associated with obesity, such as diabetes, cardiovascular disease, and cancer." (PMID 39744011, 2024). "The reason why women with PCOS are obese or gain weight may be due to variants in genes such as FTO that play an important role in the determination of body fat mass, and the association between PCOS and obesity is mediated through the effects of the latter on insulin resistance." (PMID 38907183, 2024). "Additionally, the GRGMLA haplotype might be a susceptibility factor for obesity, with significant associations between LEP and leptin receptor (LEP-R), LEP and ghrelin (GHRL), and GHRL and FTO." (PMID 39766314, 2024). "Similarly, the FTO risk variant was associated with an odds ratio of 1.97 (95% CI: 1.05-3.70, p = 0.045), further supporting its link to both GDM and type 2 diabetes, particularly due to its associations with obesity." (PMID 39469345, 2024). "Considering that ZFHX3 is located on chromosome 16, the same chromosome in which several SNPs in the FTO obesity-related gene are found, a possible hypothesis for the significant associations identified is that they might be in linkage disequilibrium with FTO and FTO-related genes." (PMID 39060932, 2024). "Hence, the present study aimed to evaluate the genetic association between FTO-rs9939609 and MAO-A 30 bp u-VNTR variants, along with personality traits and eating behavior with obesity in Mayan children from Mexico." (PMID 39130748, 2024). "Therefore, the interaction between different FTO genotypes and obesity-related factors may primarily operate through the influence of this genetic variant on eating behaviors and food cravings, rather than directly affecting fat oxidation." (PMID 39858551, 2024). "However, it is still unclear how diabetes and obesity impact FTO gene expression in the liver." (PMID 39166676, 2024). "Thus, the epigenetic regulation of FTO might also play a role in obesity development, but further replication studies with larger sample sizes as well as functional analyses are warranted." (PMID 37614712, 2023). "The FTO rs17817449 polymorphism was independently associated with both T2DM (P = 0.04) and dyslipidemia (P = 0.05) after adjusting for the confounding variables including age, sex, smoking, obesity, dyslipidemia, hyperhomocysteinemia, hyperuricemia, hypertension and CAD." (PMID 38161971, 2023). "The interaction of the FTO gene SNPs with the Iroquois homeobox 3 (IRX3) and Iroquois homeobox 5 (IRX5), genes also associated with the development of obesity and an effector of the FTO variants, may jointly regulate adipogenesis and cause white adipose tissue browning in mice." (PMID 37200795, 2023). "Likewise, there are thin and obese heterozygous individuals, which indicates that the loss or gain of the FTO function is not a condition for the development of obesity but rather specific modifications in their activity." (PMID 36672899, 2023). "Finally, although FTO is a possible genetic marker for obesity as we have discussed throughout the previous lines when comparing the results of various studies in different populations, further population studies are required to corroborate it as a genetic marker for obesity risk." (PMID 36672899, 2023). "The impact of FTO SNPs on obesity may be moderated by dietary protein intake and PA." (PMID 37664850, 2023).
Obesity (continued). "In obese and lean individuals, nonsynonymous variants of the FTO gene are found identically, suggesting that the FTO protein itself might not be the sole explanation for the association of the FTO locus with obesity in humans." (PMID 36627697, 2023). "In contrast to the finding that no FTO variants were associated with obesity risk among Black participants, the 11 FTO SNVs examined here were significantly associated with obesity phenotypes (higher in White males) and risks of hypertension and diabetes (higher in White females) in the White group." (PMID 38064210, 2023). "Interestingly, obesity was also found to be regulated by the FTO gene." (PMID 37175269, 2023). "However, the exact underlying mechanism of the effect of FTO genotype on obesity is not illustrated yet." (PMID 37752455, 2023). "However, 1 FTO SNV (rs1121980) was associated with a direct increase in the risk of heart disease in Black participants not mediated by obesity (c′ = 0.145 [SE, 0.0517]; P = .01)." (PMID 38064210, 2023). "This study aims to investigate the interaction of common FTO SNPs with actionable environmental factors, including physical activity and drinking habits (SSB and wine consumption), in determining and modifying the risk of obesity through studies of the Israeli population." (PMID 36235854, 2022). "Hence, investigations assessing the role of leptin possibly also regulating endothelial and cardiomyocyte FTO expression in obesity-related hypertension and cardiomyopathy might reveal an unrecognized mechanism within their development." (PMID 35991314, 2022). "Although FTO’s role in the development of obesity is not entirely clear, common polymorphisms in the FTO gene are strongly associated with obesity, BMI, increased energy and dietary fat intake, increased appetite and reduced satiety as well as poor food choices and eating habits." (PMID 36235854, 2022). "Moreover, the nuclear RNA N6-methyladenosine (m6A) demethylation by FTO may also be partly responsible for the effect of FTO on obesity." (PMID 35757166, 2022). "Thus, future studies in FTO might shed more light for understanding the biology of obesity, and lead to our precise understanding of how FTO plays a role in energy intake and expenditure." (PMID 35508500, 2022). "Molecularly, variation in FTO could explain the m6A perturbation found in both obesity and cancer." (PMID 35409166, 2022). "However, further experiments are required to confirm whether modulating ghrelin is sufficient to explain FTO’s molecular role in obesity." (PMID 35409166, 2022). "Overall, these results indicate that (a) individual variation in rCBF within a sample with overweight and obesity may be attributed to a common FTO variant, but (b) a weight loss intervention is effective at increasing rCBF, regardless of FTO genotype." (PMID 36072887, 2022). "Besides, other FTO inhibitors such as FB23/FB23-2, MA/MA2, MO-I-500, and, intriguingly, Entacapone have been delineated to harbor a binding ability toward FTO with the aim to reduce the RNA demethylase activity, which should have anti-cancer effects other than anti-obesity effects." (PMID 35563821, 2022). "Research has indicated that the FTO gene may play a role in cellular sensing of macronutrients and may be involved in the regulation of cell growth, which can at least partly explain its relationship with both obesity and breast cancer." (PMID 35414113, 2022). "In addition, we were able to determine correlations between individual miRNAs, miR-20a-5p, −22-5p, and −101-3p (p < 0.04), and the genetic predisposition for endurance and/or strength and obesity risk (ACE, ACTN3, and FTO), as well as between miRNAs and the body composition (p < 0.05)." (PMID 35937778, 2022). "In addition, FTO has attracted considerable attention as a pharmaceutical target because of the discovery that its overexpression links to the development of metabolic diseases such as obesity and cancers." (PMID 35398093, 2022).
Obesity (continued). "Weekly wine consumption reduced the risk of obesity by 44% (OR = 0.56) for the wild type (TT) (p = 0.009) and by 32% (OR = 0.68) for those who carried at least one FTO rs9939609 risk allele (p = 0.005) compared to their non-drinking counterparts (n = 494 and n = 1260, respectively)." (PMID 36235854, 2022). "Suggesting that, FTO may at least partially involved in this anti-obesity process." (PMID 35769384, 2022). "could be potent sources of anti-obesity compound by inhibiting the FTO protein." (PMID 36299509, 2022). "Since then, many studies have proved that the FTO variants, especially the common A/T polymorphism (rs9939609), are significantly linked to obesity-related traits, e.g., BMI, FMI, body fat percentage, hip circumference, cardiometabolic traits, and many obesity-related medical problems." (PMID 35627568, 2022). "Some tumorigenic FTO SNPs were reported to be BMI-related while others were independent of BMI; indicating that obesity may confer increased risk in some cancers, through a potentially common FTO metabolic-tumorigenic regulatory axis." (PMID 35409166, 2022). "Hence, with all the data obtained it could be concluded that three seaweed compounds, BT012, RL074 and RL442, may act as a potential anti-obesity lead compound in targeting FTO." (PMID 36299509, 2022). "The mapped genes (FTO, SLC38A11, and RNA5SP111) of the identified PCOS SNPs in our study were also associated with obesity-related traits, including WHR, WHR adjusting for BMI, and childhood BMI (CBMI), suggesting the shared genetic architecture of PCOS, T2D, and obesity." (PMID 36105080, 2022). "As most clinical data have illustrated that the risk alleles of FTO are associated with increased energy intake, our data highlight hypothalamic postnatal neurogenesis regulated by IRX3 and IRX5 as a potential mechanism affecting leptin response in human obesity." (PMID 34795556, 2021). "Therefore,it is of interest to determine the correlation between FTO gene variants rs8050136, rs17817449 and rs1421085 as risk factors for PCOS and obesity and their contribution to the severity of the disorder using association studies with different clinical PCOSvariables." (PMID 35655906, 2021). "After adjusting for age and sex, we found that rs8050136 in FTO (odds ratio [OR] 1.40, 95% confidence interval [CI] 1.1–1.8; P = 0.01) among African Americans and rs2272383 in TUB (OR 1.34, 95% CI 1.04–1.71; P = 0.02) among Hispanic/Latinos were associated with obesity." (PMID 33983957, 2021). "Furthermore, lifestyle modifications may exert their effects on obesity through changes in the expression of the FTO and IRX3 genes." (PMID 34038448, 2021). "However, there are reports that obesity-associated SNPs are not functionally related to FTO, but are related to FTO neighboring genes IRX 3 and RPGRIP1L." (PMID 34638947, 2021). "However, the underlying mechanism remained unknown until the discovery of FTO as an m6A demethylase, which accounts for most of its functions in controlling body weight, obesity and adipogenesis." (PMID 33461172, 2021). "FTO; rs9939609 has been previously reported in several other Non-Arab ethnicities in association with energy intake, eating habits, and susceptibility to obesity." (PMID 34131278, 2021). "Cumulatively, this proves that the FTO gene could play an important role not only in the development of adiposity itself, but also in the pathogenesis of obesity complications, although further studies, preferably of prospective design, would be needed to confirm these assumptions." (PMID 34063412, 2021). "Moreover, higher FTO expression has been associated with an increase of the concentration of FFA, suggesting that the FTO gene may play a role in the development of the impairment of glucose-lipid metabolism related to obesity in children." (PMID 35071145, 2021).
Obesity (continued). "While a top variant identified by GWAS was assumed to regulate FTO by a series of functional tests in 2009–2010, in 2014 it was found to interact with the promoters of IRX3 located several hundred kilobases away and obesity-associated variants were associated with IRX3 expression." (PMID 32948841, 2021). "A recent preprint identified a variant at the FTO locus as a susceptibility locus for having high ALT levels in the Million Veteran Program30 Although the biological relevance of variation at the FTO locus is still a matter of debate, FTO is a well-characterized genetic locus for obesity." (PMID 34841290, 2021). "Additionally, using chromatin conformation capture technologies, the region has been observed to establish long-range interactions with the obesity-related gene IRX3 and FTO risk alleles correlating with increased IRX3 expression and body mass index in humans, mice, and zebrafish." (PMID 32486876, 2020). "Fat mass and obesity-associated (FTO) gene is an obesity susceptibility gene and its relationship with the nonalcoholic fatty liver disease (NAFLD) remains unclear." (PMID 33817272, 2020). "This may imply the long-lasting effect of FTO risk alleles in increasing the obesity risk, regardless of the age." (PMID 31915589, 2020). "Rhein has anti-obesity effect, but it needs to be further clarified whether by inhibiting FTO." (PMID 33304380, 2020). "Our study showed that several risk variants for obesity or metabolic diseases (FTO rs1121980, KCNQ1 rs163182, MC4R rs12970134, and PROX1 rs340841) were also associated with GDM, giving further evidence that GDM and obesity/metabolic diseases may share a similar genetic background." (PMID 32390949, 2020). "Although obesity, hypertension, and genetics have been reported as main risk factors associated with ADA as well as the strong correlation between FTO gene and obesity and diabetes has been confirmed, in regards to the role of FTO in formation and progress of ADA remains unclear." (PMID 33330653, 2020). "Therefore, the aims of this nutrigenetics study were to evaluate the potential interaction between three candidate SNPs, rs1558902 and rs9939609 in the FTO gene and the rs7903146 variant of the TCF7L2 gene, and macronutrient intake with regard to obesity, body fat and muscle composition." (PMID 30764585, 2019). "A single nucleotide polymorphism (SNP) analysis study of fat mass and obesity-associated gene (FTO gene) showed a significant correlation between SNP RS 11076008 loci G/G genotype and IDD in the Han population, which suggests that obesity may be an important factor inducing IDD." (PMID 31649558, 2019). "The mechanisms responsible for the effect of the FTO gene on obesity remain unknown." (PMID 31075924, 2019). "However, little is known about the molecular mechanisms that FTO uses to induce obesity and T2D." (PMID 30764545, 2019). "In this line of evidence, we found that FTO variants associated with BMI only remained in BD patients, even when the BDC group had higher rates of obesity, which suggests that the effect of these variants modulating BMI could be higher in BD patients than in non‐BD obese individuals." (PMID 31033179, 2019). "Subsequently, reports indicate that FTO demethylates not only m6A, but also N6,2′-O-dimethyladenosine (m6Am), N1-methyladenosine (m1A), and regulate RNA stability, with findings that further support the concept of RNA modification's role in the pathogenesis of obesity." (PMID 31482095, 2019). "The study suggests that in healthy, normal-weighted males and females, altered postprandial responses in hunger hormones and metabolic flexibility may not be a mechanism by which FTO is associated with higher BMI and obesity." (PMID 31635368, 2019). "Based on previous studies, FTO gene effects on obesity may be modified by physical activity." (PMID 31075924, 2019).
Obesity (continued). "Recent evidence suggests that the LEPR-b-STAT3 signaling pathway may be involved in FTO regulation by restricting energy in the hypothalamus and there is evidence that the leptin receptor (LEPR) variant rs1137101 is positively associated with obesity." (PMID 29679223, 2018). "Therefore, it is possible that the high physical activity levels within our cohort may have diminished any differences in obesity-related parameters between FTO rs9939609 genotypes." (PMID 29686893, 2018). "The association between risk-variants of the FTO gene and obesity seems not to be mediated by peripheral factors such as a dysfunctional metabolism, but rather by increased dietary intake and unhealthy eating behaviors, probably linked to an aberrant functioning of the reward network." (PMID 29520227, 2018). "Studies on the FTO rs9939609, the MC4R rs17782313, and the PPAR-γ rs1801282 polymorphisms conducted so far, focused mainly on searching for the relationships between these gene variants and symptoms of metabolic disorders (obesity, insulin resistance, hypertension, and hyperlipidemia)." (PMID 30271660, 2018). "However, subsequent studies demonstrated that FTO variants are associated with an increased risk of type 2 diabetes at least partly independent of obesity." (PMID 30388740, 2018). "Several lines of evidence suggest obesity-linked genetic risk loci (such as DRD2 and FTO) may influence individual variation in body mass index (BMI) through neuropsychological processes reflected in alterations in activation of the striatum during reward processing." (PMID 29317597, 2018). "Moreover, future studies should investigate the relationship between hepatic FTO expression and possible nutrient and hormonal signals that regulate FTO expression (e.g., glucose and insulin) and the response of hepatic FTO expression to these signals in obesity and diabetes." (PMID 30388740, 2018). "Moreover, studies showed that FTO mRNA levels are either unchanged in adipose tissue or increased in peripheral blood cells in individuals with FTO obesity-risk alleles, compared to individuals having no risk alleles." (PMID 30388740, 2018). "Therefore, there is no doubt that there is still a robust association of the FTO expression level/function with obesity and increased body mass, though the underlying mechanism has yet to be fully elucidated." (PMID 30105001, 2018). "Additionally, Zhou and colleagues found the relationship between FTO obesity-related risk allele (rs9939609 A) and shorter telomere length only in the high, but not low, FTO methylation levels in non-diabetics." (PMID 28859657, 2017). "Nevertheless, recent GWAS have identified SNPs in the MC4R 3′ UTR region to have a strong association with obesity, with rs17782313 showing the second strongest association signal after FTO and rs129070134 showing association not just in Caucasian populations but also in Asian populations." (PMID 28615046, 2017). "The objective of the present nested case-control study was to examine the hypothesis that dietary fiber could interact with FTO SNPs (rs1121980, rs1421085, rs9939973, rs8050136, rs17817449, and rs3751812), singly and in combination, in relation to obesity phenotypes among adults." (PMID 29273742, 2017). "Therefore, based on the high prevalence of obesity in PCOS and the heritable of obesity, genes associated with obesity might play a role in pathogenesis of PCOS such as FTO gene." (PMID 28826396, 2017). "Results in a Mediterranean population suggest that education may modify the genetic susceptibility of FTO to obesity, with BMI being higher in non-university subjects compared to university subjects." (PMID 28690685, 2017). "However, whether the impact of FTO on obesity is modified by lifestyle factors, such as diet, physical activity and smoking has only been partly elucidated." (PMID 28384342, 2017).